PET117 (PET117 cytochrome c oxidase chaperone)
Synonyms: CSRP2BP; MC4DN19
Tractability: PROTAC: its protein half-life has been measured.
Gene: Protein-coding gene on chromosome 20 (18,137,863 to 18,143,169, forward strand). Ensembl gene ENSG00000232838.
Subcellular location: Mitochondrion
Pathways (Reactome):
Metabolism: Complex IV assembly
Gene Ontology:
Biological process: mitochondrial respiratory chain complex IV assembly
Cellular component: mitochondrion
Genetic constraint (gnomAD): Loss-of-function variants: 4 observed, 4.1 expected, observed/expected ratio (o/e) 0.98, 90% interval 0.47 to 1.82. That is too few expected variants to judge how well the gene tolerates losing a copy. Missense variants: 34 observed, 47.8 expected, observed/expected ratio (o/e) 0.71, 90% interval 0.54 to 0.95. Synonymous variants: 14 observed, 14 expected, observed/expected ratio (o/e) 1, 90% interval 0.66 to 1.55.
Gene-disease validity (ClinGen):
ClinGen rates the evidence that PET117 causes each of these diseases.
Leigh syndrome (autosomal recessive): Limited. A progressive neurological disease defined by specific neuropathological features associating brainstem and basal ganglia lesions.
mitochondrial disease (autosomal recessive): Limited.
Homologues: Orthologues: chimpanzee PET117 (100% identical), rabbit PET117 (90% identical), dog PET117 (89% identical), pig PET117 (88% identical), guinea pig PET117 (85% identical), mouse Pet117 (85% identical), rat Pet117 (85% identical).
Diseases named in the same sentence as PET117 in open-access papers:
PET117 is named in the same sentence as 4 diseases in open-access papers, as found by Europe PMC text mining. Sharing a sentence is not in itself a finding about the gene and the disease. The quoted sentences say what the papers report.
hepatocellular carcinoma (3 papers, 2022 to 2024). A malignant tumor that arises from hepatocytes. "In hepatocellular carcinoma (HCC), a novel prognostic signature composed of 6 key lactate metabolism-related genes (FKTN, PDSS1, PET117, PUS1, RARS1, and RNASEH1) was developed to predict the survival and tumor microenvironment of HCC patients." (PMID 38529390, 2024). "There was a bioinformatic analyse identified PET117 as hub gene related to TME and prognosis of hepatocellular Carcinoma." (PMID 36105819, 2022). "In hepatocellular carcinoma (HCC), transcriptomic data revealed a lactate metabolism-related gene signature (LMRGS) based on the expression of six genes (FKTN, PDSS1, PET117, PS1, RARS1, and RNASEH1)." (PMID 36713558, 2022).
tumor (2 papers, 2022 to 2024). "Considering the tumor heterogeneity of the two clusters, we identified six prognostic genes (PIM2, PET117, SMARCA5, TAF9, ABCB10, MKP1) among the m6A-hypoxia genes and developed a scoring system to evaluate m6A modification patterns and hypoxia status." (PMID 36105819, 2022).
mitochondrial disease (1 paper, 2017). "PET117 has not been identified as a mitochondrial disease gene before." (PMID 28386624, 2017).
PET117 also shares sentences with these, for which no sentence is quoted: Leigh syndrome (1 paper).